CSF1R (colony stimulating factor 1 receptor)
Diseases named in the same sentence as CSF1R in open-access papers (continued):
Sharing a sentence is not in itself a finding about the gene and the disease.
tauopathy (12 papers, 2019 to 2024). Neurodegenerative disorders involving deposition of abnormal tau protein isoforms (tau proteins) in neurons and glial cells in the brain. "Here, we show that CSF1R inhibitors given by multiple dosing paradigms in the Tg2541 tauopathy mouse model cause a sex-independent reduction in pathogenic tau and reversion of non-microglial gene expression patterns toward a normal wild type signature." (PMID 36624100, 2023). "To investigate the impact of Dap12 deletion on microglial response to tauopathy, we subclustered microglia expressing microglial hallmark genes Csf1r, P2ry12, and Siglech into four distinct subpopulations based on subcluster marker genes." (PMID 37961627, 2023). "Importantly, we present evidence that CSF1R inhibition reduces pathology that leads to functional improvements associated with longer lifespan and reduced behavioral deficits in tauopathy mice." (PMID 36624100, 2023). "Taken together, our data support the therapeutic modulation of microglial activation by CSF1R inhibitors as a potential approach to treating human tauopathies." (PMID 36624100, 2023). "Our study highlights several aspects of pharmacological CSF1R inhibition that bolster its therapeutic potential for human tauopathies." (PMID 36624100, 2023). "Given the dynamic nature and complexity of microglial activation, the timing of CSF1R inhibition in tauopathy and its translational relevance is still an open question." (PMID 36624100, 2023). "Our study reveals several important findings from a comprehensive evaluation of CSF1R inhibitors in preclinical models of tauopathy." (PMID 36624100, 2023). "Several studies including ours demonstrate the beneficial effect of CSF1R inhibitor-mediated microglia depletion on halting tauopathy in different tau mouse models." (PMID 33752701, 2021). "Blockade of microglial proliferation by CSF1R inhibitor JNJ-40346527 (JNJ-527) attenuated tau-induced neurodegeneration in the P301S mouse tauopathy model." (PMID 34867307, 2021). "Few compounds belonging to the proposed series were reported as CSF1R/DAPK1 inhibitors as anti-tauopathies." (PMID 31809612, 2020). "In this study, we tested the efficacy of the selective CSF1R inhibitor JNJ-40346527 (JNJ-527) in the P301S mouse tauopathy model." (PMID 31504240, 2019). "As we had demonstrated the anti-proliferative effect of JNJ-527 in ME7 mice, we investigated the potential impact of blockade on CSF1R in the P301S mouse model of tauopathy." (PMID 31504240, 2019). "Therefore, our data support some potential clinical benefit of CSF1R inhibitors for treatment, in addition to prevention, of tauopathy." (PMID 36624100, 2023). "Here, we systematically tested CSF1R inhibition using multiple drug analogs at several time points in transgenic mice developing spontaneous tauopathy, and in an inoculation model of induced tauopathy." (PMID 36624100, 2023). "Likewise, in mouse models of primary tauopathy, characterized by inclusions of the protein tau in neural cells, CSF1R inhibitors reduced pathological tau aggregation and subsequent neurodegeneration." (PMID 34603007, 2021). "However, a recent study from our group has validated the inhibition of CSF1R as a disease-modifying mechanism in the P301S mouse model of tauopathy." (PMID 32581720, 2020). "This CSF1R inhibitor has been recently shown to repolarise microglia to a homeostatic phenotype and attenuate tau-induced neurodegeneration resulting in functional improvement in the P301S mouse model of tauopathy." (PMID 32581720, 2020). "Nevertheless, because CSF1R inhibition has not been reported to be detrimental in Aβ mice, CSF1R inhibitors could ameliorate AD-related tauopathy even if caused by different disease mechanisms." (PMID 36624100, 2023).
tauopathy (continued). "However, in our study, neuroprotection occurred despite incomplete microglia depletion (~60%); upon deeper analysis, we identified distinct microglial-specific gene clusters suggesting subsets of microglia responsive to tauopathy or resilient to CSF1R inhibition." (PMID 36624100, 2023). "Additionally, CSF1R has also been reported to play a role in tauopathy." (PMID 34867307, 2021). "Similarly to what was observed upon treatment with a CSF1R antagonist, prolonged depletion of T cells (via injections of anti-CD4 and anti-CD8 depleting antibodies) reduced the levels of hyperphosphorylated tau and reduced neuronal loss in the APOE4-expressing tauopathy mouse model." (PMID 37580702, 2023). "One CSF1R inhibitor, JNJ-40346527, was successful in suppressing tauopathy development in P301S tau mice and is being tested in a Phase 1 study of AD cases (NCT04121208)." (PMID 33752701, 2021). "CSF1R inhibitor JNJ527 is a tool compound that was previously shown to attenuate microglia proliferation and provide therapeutic action in models of neurodegeneration including ME7 prion mice and in the P301S mouse tauopathy model." (PMID 37032328, 2023). "Considering that PLX eliminates more than half of the total microglial population, a parsimonious explanation for this sustained gene cluster is that they are preferentially expressed by an inert microglial subpopulation that does not respond to tauopathy or low-dose CSF1R inhibition." (PMID 36624100, 2023).
viral infection (12 papers, 2014 to 2025). "In the context of viral infection, the activation of Csf1r signaling can promote the proliferation and activation of macrophages, enhance their capacity to phagocytose and digest viruses, and play a crucial role in the antiviral immune response." (PMID 40547011, 2025). "Overall, these data suggest that PLX5622 is protective during lethal viral infection and that a CSF-1-independent mechanism of microglial proliferation during CSF1-R blockade becomes more conspicuous in WNE." (PMID 35401512, 2022). "Caution is necessary when interpreting studies employing CSF1R inhibitors to deplete microglia during viral infection, as off-target effects on peripheral immunity were observed in our study and others." (PMID 34526998, 2021). "PLX5622 has previously been reported to affect myeloid and lymphoid cells in bone marrow, spleen and blood, though this likely depends on the duration of CSF1R antagonism and context of viral infection." (PMID 34566948, 2021). "Here, we used PLX5622 in a model of WNV encephalitis to examine the effect of CSF1R antagonism in the setting of neurotropic viral infection." (PMID 30704498, 2019). "Together, these data demonstrate the impact of CSF1R antagonism on APC activation during viral infection in both the CNS and periphery and highlight the importance of microglia in orchestrating cell-mediated antiviral immunity during neurotropic infection." (PMID 30704498, 2019). "Consistent with virus-mediated mobilization of monocytes/macrophages from bone-marrow sources, viral infection resulted in increased CSF-1R levels in the spleen." (PMID 30349538, 2018). "Notably, the expression levels of the majority of these proteins increased following viral infection, with the exception of three proteins (Eif3h, Eif4h, and Csf1r), which exhibited downregulation." (PMID 40547011, 2025). "Additionally, the CSF1 signal, also originating from dendritic cells, was received by macrophages and dendritic cells via CSF3R and CSF1R, playing a role in differentiation and activation following viral infection." (PMID 38743760, 2024). "Our results demonstrate strain-specific effects of the CSF1R-microglia axis in the context of neurotropic viral infection as well as inherent differences in microglial antigen presentation and subsequent T cell crosstalk that contribute to susceptibility to neurotropic picornavirus infection." (PMID 34566948, 2021). "To investigate whether microglia are involved in the control of neurotropic virus infection, we performed selective depletion of microglia, by feeding mice the CSF1R antagonist PLX5622." (PMID 30027450, 2018).
brain tumors (11 papers, 2018 to 2025). "Previous efforts have centered on developing CSF1R inhibitors to deplete TAMs in GBM, but the results showed that CSF1R inhibition only induces a transient antitumor effect caused by the compensatory changes in macrophages after the treatment in brain tumors." (PMID 39352749, 2024). "Pharmacological depletion of brain tumor-associated macrophages with either anti-CSF1R antibodies or liposomal clodronate is effective but unselective, since it also depletes microglia." (PMID 30602457, 2019). "Here, we evaluated the effect of targeting the brain tumor microenvironment via the myeloid colony-stimulating factor-1 receptor (CSF-1R) pathway using the small molecule inhibitor BLZ945." (PMID 40760255, 2025). "It has been shown recently that brain penetrant CSF1R inhibitors have the potential to treat various neurological diseases and brain tumours effectively by directly targeting CNS myeloid cells." (PMID 39049445, 2024). "Microglial depletion has also been considered for the treatment of brain neoplasms with some mitigated results due the acquisition of resistance to CSF-1R inhibition." (PMID 34082793, 2021). "For example, anti-CSF1-R therapies in combination with IR or anti-PD-1 are currently ongoing in primary brain tumors." (PMID 30483064, 2018). "Yet, no significant change in GBM cell apoptosis response to the PD-1 and CSF-1R dual blockade treatment was observed in our study, which might be contributed by the complex reprogramming of microglia phenotypes in the brain tumor microenvironment." (PMID 32909947, 2020). "In brain tumors such as GBM, overexpression of CSF-1R TME has demonstrated to promote the recruitment of TAMs." (PMID 36555334, 2022). "Moreover, some findings on CSF-1R inhibition and anti-PD-1 agents such as PRD001 have been demonstrated to be effective in brain tumor patients." (PMID 41268299, 2025).
colon carcinoma (11 papers, 2013 to 2025). "Patients with active IBD and decreased CSF1R expression have an increased risk of developing colon cancer." (PMID 39457699, 2024). "Another recent study investigating breast and colon carcinoma models found that CSF-1/CSF-1R signaling inhibition stimulated the expansion of neo-epitope-specific T cells and promoted the development of an immune-permissive TME." (PMID 40646332, 2025). "Upon examining the RNA-seq results, we observed an upregulation of CSF1R expression, specifically in MDSCs isolated from colon cancer mouse tumor tissue." (PMID 38992688, 2024). "The simultaneous action of LNCs@CSF1R siRNA and anti-PD-1 further enhanced this augmented therapeutic effect on mice with colon cancer." (PMID 38992688, 2024). "Validating these cellular and molecular insights, our experiments in a mouse model of colon cancer elucidated the tangible therapeutic benefits of a combined regimen of LNCs@CSF1R siRNA nanocarriers and anti-PD-1 antibodies." (PMID 38992688, 2024). "To evaluate which immune cell populationswere mediating antitumor efficacy, we administered depletion antibodiesspecific for CD4, CD8α, or colony stimulating factor-1 receptor(CSF1R) to MC38 colon carcinoma-bearing mice prior to starting polymertherapy." (PMID 36313164, 2022). "Our results revealed a reduction in colon tumors after injecting LNCs@CSF1R siRNA." (PMID 38992688, 2024). "Furthermore, we assessed the abundance of CD11b + Gr-1 + MDSCs and the expression of CSF1R in tumor tissues at day 7, day 14, and day 28 after diagnosing colon cancer in mice." (PMID 38992688, 2024). "The data presented collectively suggest that the concurrent administration of LNCs@CSF1R siRNA and anti-PD-1 could enhance the therapeutic efficacy of colon cancer in mice, exhibiting potential clinical applicability." (PMID 38992688, 2024). "CSF1R expression was higher in MDSC derived from colon cancer tissue." (PMID 38992688, 2024). "Furthermore normal and adenomatous polyps and colon tumors express the CSF-1R and its expression is evident in the lamina propria macrophages of the SI." (PMID 23451116, 2013). "Subsequently, LNCs@CSF1R siRNA was intravenously injected into mice with AOM- and DSS-induced colon cancer." (PMID 38992688, 2024). "Cytokines such as CSF1 can activate RTK (CSF1R) and downstream STAT3 pathway, which can promote tumor migration and invasion in colon cancers." (PMID 35366939, 2022).
giant cell tumor (11 papers, 2010 to 2025). A benign, intermediate, or malignant tumor that arises from the bone or soft tissue. "PLX3397, a selective tyrosine kinase inhibitor of CSF-1R, is already being used in clinical settings to treat giant cell tumors in the tendon sheath that cause symptoms." (PMID 40460514, 2025). "The results from this model support clinical trials of equivalent humanized agents and anti-CSF1R small molecule drugs in cases of tenosynovial giant cell tumor refractory to conventional local therapy." (PMID 20981142, 2010). "Numerous research studies have accelerated the development of potential therapies, including the use of antibodies like anti-colony-stimulating factor receptor 1 (CSF-1R), which has shown clinical benefits for patients with diffuse multinucleated giant cell tumors." (PMID 38799159, 2024). "However, while a CSF-1R blocking antibody is clinically useful in tenosynovial giant cell tumors driven by constitutive synovial CSF-1 production, clinical trials of CSF-1R inhibitors as single agents have proven disappointing." (PMID 39588367, 2024). "A randomised phase 3 trial for tenosynovial giant cell tumour with aberrantly expressing colony-stimulating factor 1 (CSF1) showed pexidartinib as CSF1R inhibitor could improve patient symptoms and functional outcomes." (PMID 32908485, 2020). "Clinically available drugs targeting CSF1 or CSF1R include pexidartinib, which repolarizes M2 macrophages and has demonstrated safety and activity in a phase 3 trial resulting in the first available systemic therapy available for tenosynovial giant cell tumors." (PMID 38612926, 2024). "Similarly, the twelfth prediction is for CSF1R and giant cell tumors." (PMID 34888523, 2021). "Several TAM-targeting agents have successfully been tested in the clinical setting, including a selective colony-stimulating factor 1 receptor (CSF1R) inhibitor, which received FDA approval for use in patients with tenosynovial giant cell tumors." (PMID 33922556, 2021). "Anti-CSF1R monoclonal antibodies have been proposed for cancer therapy for more than 10 years, and the only one in an active phase III clinical trial is RG7155 (emactuzumab), which has been tested for tenosynovial giant cell tumors (NCT05417789)." (PMID 39516356, 2024). "DCC-3014 (vimseltinib) is another promising agent that potently inhibits CSF1R (IC50 = 2.2 nM) and is being explored in tenosynovial giant cell tumors in phase 3 clinical trials (NCT05059262), Hodgkin lymphoma (NCT05723055, phase 2), and breast cancer (NCT05491226, phase 2)." (PMID 39516356, 2024). "While blockade of the CSF-1R itself has not proven helpful in the clinic except for tenosynovial giant cell tumors, the many deleterious behaviors of TAMs can be specifically targeted, including the particularly dangerous effect they have on tumor invasion and metastasis." (PMID 39588367, 2024).
neuroblastoma (11 papers, 2016 to 2023). Neuroblastoma (NB) is the most common solid, extracranial childhood tumor. "CSF-1R blockade has also been shown to synergize with PD-1/PD-L1 checkpoint inhibition and increase antitumor efficacy in a spontaneous model of high-risk neuroblastoma." (PMID 31828566, 2019). "Of note, expression of the CD73 gene was strongly correlated with CSF-1R gene expression and predicted poor clinical outcome in patients with high-risk neuroblastoma." (PMID 28123870, 2016). "In multiple datasets of neuroblastoma patients, gene expression of CD73 correlated strongly with myeloid cell markers CD163 and CSF-1R in neuroblastoma tumors, and associated with worse survival in high-risk patients." (PMID 28123870, 2016). "As previously discussed, neuroblastoma-derived factors hinder early myeloid cell differentiation to monocytes and macrophages, promoting monocyte suppressive function via M-CSF/CSF-1R interaction." (PMID 38087370, 2023). "Intriguingly, primary human monocytes polarized into suppressive CD14+CSF-1R+ M-MDSC upon co-culture with neuroblastoma cells, mediated by tumor-originating M-CSF and attenuated through CSF-1R blockade." (PMID 38087370, 2023). "We also compared the efficacy of anti-CSF1R antibody with anti-Ly6C antibody or CL in neuroblastoma PDX model." (PMID 34496935, 2021). "Recent evidence suggests that CSF1-R infiltrating myeloid cells or monocytes correlates with poor clinical outcome in patients with neuroblastoma." (PMID 32983125, 2020). "This exciting data provides preclinical evidence that CSF1R inhibitors have therapeutic potential alone or in combination with chemotherapy or immunotherapy in neuroblastoma, and warrants further clinical investigation." (PMID 32983125, 2020). "In neuroblastoma, CSF1-R inhibition exhibited marginal benefit as a monotherapy in immunodeficient mice models but synergized with chemotherapy in combination." (PMID 31828566, 2019). "In monocytes co-cultured in the presence of neuroblastoma cells, the CSF-1R inhibitor BLZ945 partially restored HLA-DR and CD86 expression and reduced the immunosuppressive capacities of the monocytes on T cell proliferation." (PMID 31191529, 2019). "It was earlier reported that the targeting of MDSCs by use of colony stimulating factor 1 receptor blockade synergizes with α-PD-1/α-PD-L1 checkpoint inhibition in reducing murine neuroblastoma progression in vivo." (PMID 30315349, 2019). "Stimulated by the finding that CSF-1R antagonist enabled anti-PD-1 antibody to control tumor growth in the transgenic neuroblastoma mouse model (TH-MYCN), we aimed to dissect the key mechanistic events underlying this combination treatment." (PMID 28123870, 2016). "Additionally, the macrophage-colony stimulating factor (M-CSF)/colony stimulating factor 1 receptor (CSF-1R) axis was suggested to drive myeloid differentiation into M-MDSCs in neuroblastoma." (PMID 38087370, 2023). "Finally, CSF-1R+ myeloid cells are associated with negative outcomes in neuroblastoma patients." (PMID 31191529, 2019). "Similarly, depletion of human monocytes and macrophages through CSF-1R inhibition using BLZ945, in combination with anti-CSF-1R treatment, enhanced chemotherapeutic efficacy in immunodeficient NOD/SCID mice with neuroblastoma xenografts, independently of T cell contribution." (PMID 38087370, 2023). "Clinical trials aiming to validate the therapeutic benefit observed with preclinical CSF-1R-PD-1 dual inhibition using both small molecule (NCT02452424) and monoclonal antibody inhibitors (NCT02526017 and NCT02323191) are assessing responses in patients with neuroblastoma." (PMID 37993280, 2023). "Despite the relevance of the adenosine pathway in neuroblastoma, treatment of TH-MYCN mice with a combination of anti-PD-1 and anti-CD73 antibodies did not lead to tumor growth inhibition, and a triple combination with CSF-1R inhibitor BLZ945 had to be discontinued due to severe weight loss in mice." (PMID 28123870, 2016).
neuroblastoma (continued). "Although PD-1 blockade failed to control tumor growth in a transgenic murine neuroblastoma model, concurrent inhibition of colony stimulating factor 1 receptor (CSF-1R) by BLZ945 reprogrammed suppressive myeloid cells and significantly enhanced therapeutic effects." (PMID 28123870, 2016).